NAB2 (NGFI-A binding protein 2)
Diseases named in the same sentence as NAB2 in open-access papers (continued):
Sharing a sentence is not in itself a finding about the gene and the disease.
osteosarcoma (1 paper, 2017). A usually aggressive malignant bone-forming mesenchymal neoplasm, predominantly affecting adolescents and young adults. "In this case, although the initial diagnosis was osteosarcoma, a re-examination that included immunohistochemical detection of STAT6 and RT-PCR detection of the NAB2 exon 6-STAT6 exon 16 fusion led us to confirm a diagnosis of malignant SFT." (PMID 28494796, 2017).
spinocerebellar ataxia type 12 (1 paper, 2023). Spinocerebellar ataxia type 12 (SCA12) is a very rare subtype of type I autosomal dominant cerebellar ataxia (ADCA type I). "One potential candidate mRNA of this type is Wwox, which encodes a conserved WW-domain oxidoreductase that accumulates in brains of Nab2 mutant flies and is mutated in human spinocerebellar ataxia type 12." (PMID 37458420, 2023).
Wilms tumor (1 paper, 2017). An embryonal neoplasm characterized by the presence of epithelial, mesenchymal, and blastema components. "Our conclusion, that NAB2 is a target gene of WT1 in leukemic cells, is consistent with data from a global genome screening, indicating that WT1 binds to the NAB2 gene in a Wilms' tumor cell line." (PMID 29152069, 2017).
α-synucleinopathy (1 paper, 2019). "In Drosophila and rat models of α-synucleinopathy, Nedd4 overexpression prevents neuronal dysfunction and pathology, and NAB2, an activator of the Nedd4 pathway, rescues α-synuclein toxicity in vitro in both yeast and human neuron α-synucleinopathy models." (PMID 31331333, 2019).
tumor (25 papers, 2007 to 2026). "The hallmark sign of the tumor is the NAB2::STAT6 fusion oncogene (NAB2: NGFI-A-binding protein 2; STAT6: signal transduction and activator of transcription 6)." (PMID 38392213, 2024). "Combined with the results of genetic testing of the patient, the tumor was indicated to carry NGFI-A-Binding protein 2(NAB2): exon 6-STAT6: exon 16 mutation sites, which confirmed our diagnosis." (PMID 36465355, 2022). "We first examined the primary tumor cells that we profiled by ChIP-seq and retrieved a robust nuclear signal for NAB2 and STAT6." (PMID 40875449, 2025). "EGR1 can modulate the expression of growth factors, such as IGF2 and TGF-β1, as well as that of NAB2, and is believed to act either as an oncogene or tumor suppressor depending on the cellular context." (PMID 40875449, 2025). "This tumor expressed the short isoform of NAB2-STAT6 containing exons 1–6 of NAB2 and exons 17–22 of STAT6." (PMID 40875449, 2025). "The tumor cells carry a NAB2:STAT6 gene fusion, which is a result of a paracentric inversion involving chromosome 12q13." (PMID 36805296, 2023). "Two nodes of module 1,” U2AF1” and “BCL1”, are oncogenes and “NAB2” is a tumor suppressor and “VTI1A” is a fusion gene." (PMID 35525925, 2022). "MIR205HG is a low degree node in the STAD network, but it has a strong expression correlation with NAB2 tumor suppressor." (PMID 35525925, 2022). "In particular, MAOB + NAB2 showed an AUC of 0.91 in the under–60 age group of non-tumor and cancer patients together." (PMID 31963366, 2020). "The human NAB2 gene is located on chromosome 12q13.3–14.1, a region that shows rearrangements in several tumor types." (PMID 31963366, 2020). "The human NAB2 gene is localized to chromosome 12q13.3–14.1, a region that is rearranged in several tumor tissues." (PMID 30845713, 2019). "Our data suggest that NAB2 upregulation facilitates EGF-mediated cancer cell invasion through the transactivation of Sp1-dependent tumor-promoting genes." (PMID 30845713, 2019). "The human NAB2 gene is located on chromosome 12ql3.3–14.1, a region that is rearranged in several tumor types." (PMID 30893927, 2019). "NAB2-positive immunoreactivity was significantly higher in CAFs as compared to tumor cells both in primary tumors and metastatic lymph node tissues." (PMID 30893927, 2019). "In contrast, NAB2 was highly expressed in interstitial CAFs of primary tumor and metastatic lymph node (red arrows) as compared to their cancer cells (black arrows)." (PMID 30893927, 2019). "NAB2-positive tumor cells and CAFs were counted in primary tumor tissues and metastatic lymph nodes, respectively." (PMID 30893927, 2019). "To evaluate the effect of CAF-derived NAB2 on FaDu cell progression in vivo, we transplanted FaDu spheroids along with P3 CAFs transfected with NAB2 or a control vector into nude mice and evaluated tumor growth over time." (PMID 30893927, 2019). "Both specimens of this tumor were tested by PCR and showed an NAB2 exon 6–STAT6 exon 16 fusion." (PMID 30584643, 2019). "Dysregulation of NAB2 will involve unregulated activity of EGR resulting in tumor growth." (PMID 17207284, 2007). "NAB2, CYP27A1, NPIPB4, MAOB, and SIAE, demonstrated lower expression for the OSCC group compared with a non-tumor group." (PMID 40723410, 2025). "Our data suggest that upregulation of NAB2, a corepressor of EGR1, permits EGF-mediated cancer invasion during conditions of EGR1 overexpression through the transactivation of Sp1-dependent tumor-promoting genes." (PMID 30845713, 2019). "To investigate the effect of NAB2 derived from CAFs on HNSCC cell invasion, we used a co-culture system to mimic the tumor microenvironment, including 2-D cancer cells and patients;’ CAF in vitro." (PMID 30893927, 2019). "NGFI-A binding protein 2 (NAB2) represses the transcriptional activation of early growth response protein-1 (EGR1), a tumor-suppressor." (PMID 30845713, 2019).
tumor (continued). "We also observed that a number of genes with tumor suppressor function (GPRC5A, ELF1, NAB2, Sema4D, ACPP, MAP2, RUNX1) persistently remained downregulated in response to radiation exposure." (PMID 23216862, 2012). "NAB2 is a corepressor of EGR (early growth response gene) and its expression depends on tumor types and stages." (PMID 17207284, 2007). "Expressions of the remaining three genes (NAB2, EHD1 and LSP1) are either upregulated or downregulated in the various tumors and also in SRBCTs depending on the tumor subgroups." (PMID 17207284, 2007). "We identified 6284 NAB2 peaks, 1640 STAT6 peaks, and 38,036 RNAPII peaks in primary tumor cells." (PMID 40875449, 2025). "In our experience, two tumor diagnoses were revised based on the NGS finding of NAB2::STAT6 fusion (patient #32) and absence of MN1 alteration (patient #30)." (PMID 38440233, 2024). "In the present study, NAB2 immunoreactivity was detected in interstitial CAFs of primary and metastatic lymph nodes, whereas tumor cells and NTFs were negative for NAB2 expression." (PMID 30893927, 2019). "In addition, NAB2 upregulation in EGF-treated FaDu cell diminishes EGR1 transcriptional activity, resulting in the upregulation of Sp1-dependent tumor-promoting genes." (PMID 30845713, 2019). "IHC revealed that the tumor diffusely expressed CD34, CD99, Bcl2, PAX8, NAB2, STAT6, and GRIA2." (PMID 26337721, 2015). "Non-tumor fibroblasts (NTFs) were negative for NAB2 expression in both tissue groups." (PMID 30893927, 2019).
cancer (10 papers, 2007 to 2024). A tumor composed of atypical neoplastic, often pleomorphic cells that invade other tissues. "Accordingly, the mRNA expression of genes associated with cancer invasion was increased in tumors in the right cheek, suggesting that NAB2 overexpressed by CAFs enhances FaDu cell progression in vivo." (PMID 30893927, 2019). "Furthermore, even though the importance of EGR1 is recognized with respect to cancer progression, the detailed mechanism regarding the action of NAB2 in association with EGR1 is largely unknown." (PMID 30845713, 2019). "Our data suggests that the molecular mechanisms by which NAB2 affects ECM in a cancer microenvironment are presumed to be different from the action of NAB2 known in other tissues so far." (PMID 30893927, 2019). "It is generally known that MMP expression in CAFs is important for cancer progression, although further studies are needed to clarify the molecular basis for NAB2-dependent MMP upregulation in CAFs." (PMID 30893927, 2019). "Further study that examines how NAB2 increases MMP2 in a cancer microenvironment, the expression of CAF markers in fibroblast cells is particularly needed." (PMID 30893927, 2019). "We propose that NAB2 represents a valid alternative to poly(I:C) as nucleic acid-sensor agonist, with a potentially improved efficacy in the immune-based treatments of cancer and as vaccine adjuvant." (PMID 29464024, 2018). "Our data indicate that NAB2 represents a novel immune stimulant with a high therapeutic potential, especially in the context of cancer immunotherapy, although further studies are needed to test the adjuvant potential of NAB2 in vivo." (PMID 29464024, 2018). "In conclusion, considering the strong type I IFN response induced, NAB2 has the potential to be a more efficient adjuvant than poly(I:C) for therapeutic immunization against cancer or infections." (PMID 29464024, 2018). "In carcinoma cells, a GC-rich NAB2 proximal promoter located within 600 bp upstream of the transcription start site (TSS) has been functionally defined, including several Egr1/Sp1 response elements." (PMID 29152069, 2017). "The upregulation of EHD1 and NAB2 clearly reveals the cancer-specific characteristic signatures of the identified genes." (PMID 17207284, 2007). "Notably, 74 of these genes overlapped with well-known cancer-associated genes (CAGs), such as CCR4, KLF4, FANCG, and NAB2." (PMID 39267784, 2024). "However, there are no previous data explaining the expression and function of NAB2 in cancer metastasis, and the in vivo functions of NAB2 are incompletely understood." (PMID 30893927, 2019). "It is necessary to investigate whether NAB2 regulates cancer progression through collagen in cancer microenvironment." (PMID 30893927, 2019). "The molecular mechanism through which NAB2 is involved in cancer is largely unknown." (PMID 30845713, 2019). "The fusion of two genes on chromosome 12 – NAB2 and STAT6 – has been found in a rare form of cancer, known as a solitary fibrous tumor, which can form in almost any part of the body." (PMID 39370970, 2024). "Future research on the molecular consequences of the fusion of NAB2 and STAT6 may help refine cancer diagnosis and inform drug development." (PMID 39370970, 2024). "This nonhereditary cancer is the result of an environmental intrachromosomal gene fusion between NAB2 and STAT6 on chromosome 12." (PMID 37370737, 2023). "This nonhereditary cancer is the result of an environmental intrachromosomal gene fusion between NAB2 and STAT6 on chromosome 12, which fuses the activation domain of STAT6 with the repression domain of NAB2." (PMID 37370737, 2023).
peripheral neuropathy (1 paper, 2009). A disorder affecting the peripheral nervous system. "Although Nab2 has been implicated in macrophage development, cardiac hypertrophy, peripheral neuropathy and prostate cancer, to date its in vivo functions are poorly understood." (PMID 19888474, 2009). "In previous studies, mice deleted for Nab2 appeared to have no obvious phenotype, whereas mice lacking both Nab1 and Nab2 developed peripheral neuropathy and abnormalities in skin development, and suffered from early lethality." (PMID 19888474, 2009).
NAB2 also shares sentences with these, for which no sentence is quoted: Hypoglycemia (2 papers); angiomatoid fibrous histiocytoma (1); autosomal recessive intellectual disability (1); cognitive defects (1); congenital mesoblastic nephroma (1); Constipation (1); Dyskinesia (1); dyslexia (1); fibrosis (1); glioblastoma (1); infection (1); metastatic tumors (1); microencephaly (1); neuroblastoma (1); neurological disease (1); non-Hodgkin lymphoma (1); rhabdomyosarcoma (1); sarcoma (1); soft tissue sarcoma (1); synovial sarcoma (1).